HMGN1 (high mobility group nucleosome binding domain 1)
Description:
Binds to the inner side of the nucleosomal DNA thus altering the interaction between the DNA and the histone octamer. May be involved in the process which maintains transcribable genes in a unique chromatin conformation. Inhibits the phosphorylation of nucleosomal histones H3 and H2A by RPS6KA5/MSK1 and RPS6KA3/RSK2 (By similarity).
Synonyms: HMG14; FLJ27265; FLJ31471; MGC104230; MGC117425
Tractability: PROTAC: ubiquitination databases record sites on it; its protein half-life has been measured.
Gene: Protein-coding gene on chromosome 21 (39,342,315 to 39,349,653, reverse strand). Ensembl gene ENSG00000205581.
Subcellular location: Nucleus; Cytoplasm
Subcellular location (Human Protein Atlas): Nucleoplasm
Gene Ontology:
Molecular function: protein binding; chromatin binding; DNA binding; nucleosomal DNA binding
Biological process: chromatin organization; positive regulation of DNA-templated transcription, elongation
Cellular component: nucleoplasm; nucleus; chromatin; cytoplasm
Genetic constraint (gnomAD): Loss-of-function variants: 8 observed, 16.14 expected, observed/expected ratio (o/e) 0.5, 90% interval 0.29 to 0.89. The upper end of that interval is the gene's LOEUF score, 0.89, which puts it in group 3 of 6, group 1 being the genes least tolerant of losing a copy. Missense variants: 133 observed, 103.16 expected, observed/expected ratio (o/e) 1.29, 90% interval 1.12 to 1.49. Synonymous variants: 53 observed, 41.77 expected, observed/expected ratio (o/e) 1.27, 90% interval 1.02 to 1.6.
Homologues: Orthologues: macaque HMGN1 (100% identical), guinea pig HMGN1 (87% identical), pig HMGN1 (83% identical), rat Hmgn1 (79% identical), mouse Hmgn1 (78% identical), rat Hmgn1l1 (68% identical), tropical clawed frog hmgn1 (64% identical), zebrafish hmgn6 (45% identical). Paralogues in human: HMGN2 (55% identical), HMGN4 (47% identical), HMGN3 (46% identical).
Diseases named in the same sentence as HMGN1 in open-access papers:
HMGN1 is named in the same sentence as 68 diseases in open-access papers, as found by Europe PMC text mining. Sharing a sentence is not in itself a finding about the gene and the disease. The quoted sentences say what the papers report.
breast carcinoma (9 papers, 2014 to 2025). "It was also noted that the HMGN1 expression was elevated in the gastric and breast cancer samples compared to the paraneoplastic tissues." (PMID 38310387, 2025). "RT-PCR assays indicated that HMGN1 was overexpressed in the gastric and breast cancer cell lines and tissues." (PMID 38310387, 2025). "High cytoplasmic HMGN1 expression was associated with prominent histological grade and levels of tumor-infiltering lymphocytes in HER2-positive breast cancer tissues." (PMID 34298646, 2021). "HMGN1 expression was significant in highly metastatic MDA-MB-435 cells from breast cancer cell lines." (PMID 34298646, 2021). "Furthermore, the findings of the PCR experiments indicated that HMGN1 was over-expressed in the gastric and breast cancer cell lines in comparison to the healthy cell lines." (PMID 38310387, 2025). "Likewise, HMGN1 expression was reduced in exosomes from pancreatic and breast cancer patients’ serum compared with normal volunteers." (PMID 32286296, 2020). "HMGB1 and HMGN1 are important nuclear DAMPs, and their translocation to the cytoplasm can activate proinflammatory signaling by binding to PRRs, resulting in TIL influx in breast cancer." (PMID 35444934, 2022). "In addition to HMGN1, the expression of HMGN5 (formerly NSBP1) was found to be elevated 4-fold in highly metastatic breast cancer cells compared with that in low metastatic cells." (PMID 25060707, 2014). "In addition to HMGN1, the expression of HMGN5 (formerly NSBP1) was found to be elevated four-fold in highly metastatic breast cancer cells compared with that in low metastatic cells." (PMID 24348831, 2014). "To place the observed HMGN1 downregulation in a biologically meaningful context, we examined the role of this gene in breast-cancer dormancy — an epigenetic-driven, non-replicative state, from which cancer cells “awaken”, causing cancer relapse and resistance to therapy." (PMID 41366211, 2025).
Down syndrome (9 papers, 2014 to 2025). "In Down syndrome, one of the most prevalent human genetic diseases, the presence of an extra copy of HMGN1 has been directly linked to increased levels of H3K27ac and to gene expression changes and to increased incidence of acute lymphoblastic leukemia." (PMID 35197580, 2022). "The only direct correlation between changes in HMGN expression and a human phenotype is Down syndrome where an increase in HMGN1 has been shown to correlate with increased incidence of B-ALL." (PMID 31936777, 2020). "The human HMGN1 gene is located in chromosome 21 in a segment known as the Down Syndrome critical region (DSCR), which is thought to play an important role in the etiology of this syndrome." (PMID 31936777, 2020). "The HMGN1 gene is located in a region of human chromosome 21 that is most frequently triplicated in Down syndrome, and tissue samples obtained from Down syndrome individuals overexpress HMGN1 protein." (PMID 31936777, 2020). "We previously performed an RNA interference screen in murine B cell progenitors modeling Down syndrome and found that Hmgn1 was the amplified gene most critical to support hematopoietic colony forming activity." (PMID 32179749, 2020). "In mice, Hmgn1 is located on chromosome 16 and is trisomic in several models of Down syndrome, including Ts1Rhr22, which triplicates 31 genes orthologous to a segment of human chr21q22 that is recurrently amplified in AML." (PMID 32179749, 2020). "Elevated HMGN1 expression is observed in human Down Syndrome cells and in cells from Ts1Cje mouse, which is used as a model for Down Syndrome." (PMID 31936777, 2020). "In humans, the increase incidents of B cells acute lymphoblastic leukemia seen in Down syndrome was directly attributed to epigenetic changes and altered transcription mediated by increased HMGN1 levels due to the extra copy of HMGN1, which is located on human chromosome 2125,54." (PMID 35197580, 2022). "It is overexpressed in Down syndrome and it has been suggested that epigenetic changes resulting from altered HMGN1 levels could have a role in the etiology of several neurodevelopmental disorders including autism and Down syndrome." (PMID 25644384, 2015). "Among the pathways altered by prenatal stress was HMGN1 (high-mobility group nucleosome binding domain 1), a nuclear protein involved in compaction of chromatin, histone modifications, DNA repair and epigenetic regulation of neurodevelopmental diseases, such as Down syndrome." (PMID 24651125, 2014). "The mouse models for Down syndrome express approximately 1.5-fold higher levels of HMGN1 mRNA and protein, as compared to normal littermates; however, it is not clear whether the neurological phenotypes seen in Down syndrome individuals are directly linked to elevated HMGN1 levels." (PMID 31936777, 2020).
hepatocellular carcinoma (6 papers, 2021 to 2025). A malignant tumor that arises from hepatocytes. "In a murine Hepa1-6 hepatoma model, a regimen consisting of HMGN1, resiquimod and a checkpoint inhibitor resulted in the elimination of established tumors and protected the mice against tumor rechallenge." (PMID 34025657, 2021). "For instance, engineered DEXs with hepatocellular carcinoma (HCC)-targeting peptide P47, the immunoadjuvant high-mobility group nucleosome-binding protein 1 (HMGN1), and an α-fetoprotein epitope." (PMID 39961904, 2025). "In other studies on hepatocellular carcinoma (HCC), TEX incorporated with other molecules such as miR-155 and high-mobility group nucleosome-binding protein 1 (HMGN1) have also improved DCs’ maturation and antigen presentation." (PMID 38473281, 2024). "Thus, the intratumoral delivery of HMGN1, the TLR7/8 agonist Resiquimod and checkpoint inhibitors cured established subcutaneous hepatomas and protected the mice against tumor rechallenge (see also TLR7/8)." (PMID 34025657, 2021). "TEX loaded with the N-terminus of HMGN1 (NIND) could activate DCs; these pulsed DCs significantly suppressed tumor growth through elevation of CD8+T cells and reduction of Treg cells in multiple cancer types, including hepatocellular carcinoma (HCC), pancreatic cancer and breast cancer." (PMID 36109501, 2022).
leukemia (6 papers, 2020 to 2025). A malignant (clonal) hematologic disorder, involving hematopoietic stem cells and characterized by the presence of primitive or atypical myeloid or lymphoid cells in the bone marrow and the blood. "Here, the authors show that the chromatin accessibility regulator HMGN1 - which is frequently mutated by amplification in leukemias - acts by blocking myeloid differentiation." (PMID 32179749, 2020). "We found that HMGN1 blocks differentiation, enhances stem cell properties, and cooperates with leukemia-associated oncogenes." (PMID 32179749, 2020). "It was also reported that HMGN1 amplification is also associated with increased chromatin accessibility; It conferred a transcriptional and chromatin phenotype associated with stem cells and leukemia." (PMID 39746113, 2025). "The expansion of phenotypically immature leukemia cells led us to hypothesize that HMGN1 overexpressing leukemias might be associated with increased LSC activity." (PMID 32179749, 2020). "HMGN1 promoted histone acetylation globally and even more so focally at leukemia-associated loci." (PMID 32179749, 2020). "The functional relationship between HMGN1 and carcinogenesis, including leukemia and stomach cancer, has been highlighted in recent studies." (PMID 38310387, 2025). "HMGN1 overexpression increases chromatin accessibility, expression, and H3K27ac at loci important for HSCs and leukemia, including many CREBBP/EP300 targets." (PMID 36831561, 2023). "Interest in the potential involvement of HMGN1 in leukemia development has arisen due to its demethylase activity associated with enhanced transcriptional activation." (PMID 37483494, 2023). "HMGN1 is the chromatin accessibility regulator and a target of recurrent DNA copy gains in leukemia." (PMID 36035173, 2022). "Treatment with HAT inhibitors reversed the HSPC-like expansion and promoted terminal differentiation in HMGN1-OE AML-ETO9a leukemias." (PMID 32179749, 2020). "HMGN1-OE leukemias were enriched for LSK-like cells and particularly for the LSK subset having a multipotent progenitor (MPP)-like phenotype (Lin− CD117+ Sca-1+ CD150+ CD48−)." (PMID 32179749, 2020). "Here, we report that the chromatin accessibility regulator HMGN1, a target of recurrent DNA copy gains in leukemia, controls myeloid differentiation." (PMID 32179749, 2020). "Together, these data suggest that HAT inhibition selectively restores differentiation in HMGN1-overexpressing hematopoietic progenitors and leukemias." (PMID 32179749, 2020). "Consistent with this prediction, in long-term culture initiating cell (LTC-IC) assays, an in vitro measure of HSPC activity that also correlates with survival in human AML42, HMGN1-OE plus AML-ETO9a leukemias had increased colony formation capacity." (PMID 32179749, 2020). "This suggested that HMGN1-overexpressing leukemias had a larger proportion of primitive, stem-like cells compared to wild-type leukemias." (PMID 32179749, 2020). "Similar to what we observed with preleukemic HSPCs, the relative fractions of primitive LK cells were expanded and terminally differentiated GR-1+ cells were reduced in myeloid-biased cultures of HMGN1-OE AML-ETO9a leukemia cells." (PMID 32179749, 2020). "HMGN1 has also been identified as a target of recurrent DNA copy increase in leukemia, and the mechanisms that combined HMGN1 overexpression and the AML-ETO9a fusion oncoprotein could hinder bone marrow differentiation and promote leukemic stem cell activity." (PMID 38310387, 2025). "Finally, we tested HAT inhibition with C646 and A-485 in AML-ETO9a leukemia cells derived from wild-type or HMGN1-OE bone marrow." (PMID 32179749, 2020). "HMGN1 amplification is associated with increased accessibility, expression, and histone H3K27 acetylation of loci important for hematopoietic stem cells (HSCs) and leukemia, such as HoxA cluster genes." (PMID 32179749, 2020).
leukemia (continued). "Moreover, HMGN1 overexpression promotes a clonal advantage in HSPCs in vivo and increases leukemia stem cell (LSC) activity in concert with AML oncogenes." (PMID 32179749, 2020). "HMGN1 increases accessible chromatin and expression-associated chromatin marks at lineage-specific loci, and here, similarly, we found it promoted increased expression of HSC and leukemia-associated genes in myeloid progenitors." (PMID 32179749, 2020). "HMGN1 overexpression impaired myeloid differentiation and conferred a competitive advantage to HSPCs but did not cause leukemia on its own (up to 18 months of observation)." (PMID 32179749, 2020). "In AML, 21q22/HMGN1 amplification cooperates with the AML-ETO9a to impair myeloid differentiation and enhance leukemia stem cell activity." (PMID 36831561, 2023). "Overall, HMGN1 and CHAF1B block myeloid differentiation and promote leukemia growth in other contexts but their roles in the initiation of TAM and progression to ML-DS are not known." (PMID 36035173, 2022). "HMGN1 overexpression also cooperates with the AML-ETO9a fusion oncoprotein to impair myeloid differentiation and enhance leukemia stem cell (LSC) activity." (PMID 32179749, 2020). "Together, these data suggest that the effects of HMGN1 in myeloid progenitors are most prominent at genes that are important in myeloid differentiation, HSC function, and leukemia, including but not limited to, Hox transcription factors." (PMID 32179749, 2020). "Thus, HMGN1 overexpression increased LSC frequency and capacity to transplant a fatal HSPC-like immature leukemia in AML-ETO9a cells." (PMID 32179749, 2020). "Moreover, similar to what we had observed in HMGN1-OE ex vivo immortalized progenitors and HSPCs in vivo, HMGN1-OE plus AML-ETO9a leukemias had increased H3K27 acetylation, particularly within the subset of leukemia cells that had an HSC-like phenotype." (PMID 32179749, 2020). "In the absence of a direct inhibitor of HMGN1, HAT inhibition may be active in leukemias associated with chr21 amplification or alterations resulting in similar chromatin phenotypes." (PMID 32179749, 2020).
thymoma (4 papers, 2017 to 2025). A neoplasm arising from the epithelial cells of the thymus. "Particularly, HMGN1 has been shown to be critical for the generation of anti-tumor immunity against mouse thymoma and melanoma." (PMID 30619746, 2018). "HMGN1 is effective in preventing the growth of mouse thymoma and melanoma." (PMID 28881713, 2017).
Anxiety (3 papers, 2020 to 2021). Intense feelings of nervousness, tension, or panic often arise in response to interpersonal stresses. "Behavior analyses by open field test, elevated plus maze, reciprocal social interaction, and automated sociability test, link changes in HMGN1 levels to abnormalities in activity and anxiety and to social deficits in mice." (PMID 31936777, 2020). "Changes in the expression level of Hmgn1 can lead to abnormal activity and anxiety in mice." (PMID 32392183, 2020).
autism (3 papers, 2015 to 2022). Persistent deficits in social interaction and communication and interaction as well as a markedly restricted repertoire of activity and interest as well as repetitive patterns of behavior. "The most profound findings of this work led to the discovery that changes in the level of HMGN1 can lead to autism-related behaviors." (PMID 36463299, 2022).
B-cell acute lymphoblastic leukemia (3 papers, 2017 to 2022). A neoplasm of lymphoblasts committed to the B-cell lineage, typically composed of small to medium-sized blast cells. "Recent studies causatively linked overexpression of HMGN1 in trisomy and the development of DS-associated B cell acute lymphoblastic leukemia (B-ALL)." (PMID 36463299, 2022). "In B-cell acute lymphoblastic leukemia, overexpression of the nucleosome remodeling protein HMGN1 suppresses heterochromatin marker H3K27me3 levels and promotes B cell transcriptomic levels and proliferation." (PMID 34159316, 2021).
colon tumors (3 papers, 2017 to 2023). "The combination of ansofaxine hydrochloride and HMGN1 and 3M-052 (As-NM) effectively inhibited the growth of colon tumors, and one mouse was tumor-free and survived for 80 days." (PMID 38161697, 2023).
gastric cancer (3 papers, 2022 to 2024). A primary or metastatic malignant neoplasm involving the stomach. "Finally, pan-cancer analysis across various cancers, including breast, colon, liver, and stomach cancers, also indicated high expression of HMGN1." (PMID 38710740, 2024). "High rates of expression of HMGB3, HMGN1, HMGN2, HMGN3, and HMGN4 are shown in gastric cancer." (PMID 39062899, 2024).
lung carcinoma (3 papers, 2019 to 2025). "And we analyzed the diagnostic efficiency of HMGN1 expression in discriminating LUAD patients from other lung cancer using ROC curves from GEO dataset." (PMID 38710740, 2024). "Since the prognostic significance of HMGN1 in lung cancer and other cancers, we examined the prognostic potency of HMGN1 for LMS patients." (PMID 30984618, 2019). "Furthermore, HMGN1 expression in four major subtypes of lung cancer was significantly higher than normal control." (PMID 38710740, 2024). "First, the relationship between HMGN1 mRNA levels and clinicopathological subgroups of LUAD patients was evaluated in the TCGA lung cancer and GSE11969 cohorts." (PMID 38710740, 2024).
melanoma (3 papers, 2018 to 2024). A malignant, usually aggressive tumor composed of atypical, neoplastic melanocytes. "This was accompanied by a reduction of HMGB1 and HMGN1 in melanoma cell lysates, indicating that LTX-315 treatment results in the translocation/release of both these DAMPs/alarmins from A375 and B16F10 cells into the supernatant." (PMID 38545099, 2024). "Among the high‐mobility chromosomal proteins, worthy of mention as an alarmin in melanoma is HMGN1." (PMID 38775220, 2024).
non-small cell lung carcinoma (3 papers, 2019 to 2020). A group of at least three distinct histological types of lung cancer, including non-small cell squamous cell carcinoma, adenocarcinoma, and large cell carcinoma. "In non-small cell lung cancer (NSCLC) patients, the levels of HMGN1 in the serum were correlated with overall survival after curative pneumonectomy." (PMID 31936777, 2020).
prostate carcinoma (3 papers, 2011 to 2025). A carcinoma that arises from epithelial cells of the prostate gland. "More importantly, the HMGN1 fusions with GBE and A8e also enhanced the editing yield in HeLa cells and exhibited substantial C-to-G and A-to-G transition in primary prostate carcinoma cells." (PMID 37105976, 2023).
autism spectrum disorder (2 papers, 2015 to 2020). A spectrum of developmental disorders that includes autism, and Asperger syndrome. "Targeted analysis of the Autism Genetic Resource Exchange genotype collection revealed a non-random distribution of genotypes within 500 kbp of HMGN1 in a region affecting its expression in families predisposed to autism spectrum disorders." (PMID 31936777, 2020).